INS (insulin)
Diseases named in the same sentence as INS in open-access papers (continued):
Sharing a sentence is not in itself a finding about the gene and the disease.
Insulin resistance (continued). "Our results revealed an association between LFC and glucose metabolism status, where the excessive accumulation of liver fat strongly correlated with insulin resistance, impaired insulin secretive function and abnormality of glucose metabolism." (PMID 32528557, 2020). "In untreated obese mice, vascular insulin resistance seemed to be mediated by ET-1, since insulin-induced vasodilation was improved in the presence of the ET-A blocker BQ-123." (PMID 32326269, 2020). "Obesity is often associated with glucose intolerance, elevated leptin, glucose and insulin blood levels, and insulin resistance." (PMID 32244932, 2020). "In this study, we used DEX combined with insulin to induce a cell model of insulin resistance on adipocytes and explored the effects of flavonoids of mulberry leaves on it." (PMID 31908653, 2020). "Glucose homeostasis is maintained by insulin and glucagon, whereas disrupted pancreatic islet functions and insulin resistance in T2D leads to glucose intolerance." (PMID 33192521, 2020). "The results showed that maternal HFD intake significantly increased the serum insulin levels (p < 0.01) and the homeostasis model assessment of insulin resistance (HOMA-IR) index (p < 0.05) in the mothers per se compared with those fed the control diet." (PMID 32626663, 2020). "Mice fed with a high-fructose diet developed hepatic insulin resistance due to inhibition of insulin-mediated Akt phosphorylation by IRE1-JNK pathway and diet-impaired hepatic insulin signaling." (PMID 32397116, 2020). "In this regard, excessive carbohydrate intake and exposure to insulin (such as in insulin resistance) trigger acute epigenetic changes in tissues involved in glucose uptake (e.g., skeletal muscle)." (PMID 33333828, 2020). "NR4As have been reported to regulate glucose production and utilization, lipid metabolism, and mitochondrial function as well as insulin secretion and insulin resistance." (PMID 33328994, 2020). "Lipid accumulation in the liver leads to impaired insulin signaling and insulin resistance, which are key symptoms of NAFLD progression." (PMID 32148789, 2020). "Gestational Diabetes Mellitus (GDM) is characterised by insulin resistance accompanied by reduced beta-cell compensation to increased insulin demand, typically observed in the second and third trimester and associated with adverse pregnancy outcomes." (PMID 31969632, 2020). "Some of these adipokines, such as resistin and leptin, antagonize insulin function in peripheral tissues, especially in the liver and skeletal muscles, which leads to insulin resistance." (PMID 32714446, 2020). "No significant improvements were observed in plasma glucose, insulin, and the homeostatic model assessment of insulin resistance (HOMA-IR) after exercise training." (PMID 33192562, 2020). "Compared with non-OSA, patients with OSA were older and had higher serum concentrations of glucose, insulin, sleep parameters and ratio of smoking, drinking, prevalence of insulin resistance and percentage of MetS." (PMID 33005209, 2020). "Insulin resistance is a pathological condition characterized by disruption of insulin effects in peripheral tissues including the skeletal muscle, liver, and adipose tissue." (PMID 32907593, 2020). "After prolonged exposure to IL-1β in vitro, induced insulin resistance has been reported in murine and human adipocytes through a decrease in the expression of the glucose transporter Glut 4, which ultimately impairs insulin signaling and action." (PMID 33028018, 2020). "Brain insulin resistance is unfavourable, as brain insulin resistant individuals show a reduced capacity for weight loss during a lifestyle intervention program." (PMID 33047031, 2020). "Peripubertal letrozole-induced PCOS rats and mice also have increased fasting glucose and insulin levels and develop insulin resistance in adulthood as measured by insulin tolerance test and euglycemic hyperinsulinemic clamp." (PMID 32310267, 2020).
Insulin resistance (continued). "HOMA-IR value for NPD was within the insulin-sensitive range (< 1.0) while the PD group had a significantly higher HOMA-IR value compared to the PD which was in the range of significant insulin resistance." (PMID 33308255, 2020). "Persistent elevation of serum insulin as evident in individuals with insulin resistance, interferes with insulin activity and glucose uptake and free fatty acid esterification due to impairment of insulin mediated suppression of hormone sensitive lipase." (PMID 32366255, 2020). "The magnitude of reduction in insulin tAUC from SIT-to-EX+BR was greater in those with increased basal insulin resistance." (PMID 33308235, 2020). "Insulin resistance is blamed for the failure of normal or elevated levels of insulin to regulate glucose." (PMID 33365205, 2020). "Insulin resistance can be defined as a condition in which the pancreas is required to secrete more insulin than normal in order to achieve normal blood glucose levels due to reduced sensitivity or responsiveness of tissues to insulin biologic activity." (PMID 32522257, 2020). "The basic characteristics of insulin, insulin resistance, and TG were lower in the highest quintile of APOA GRS than in the lowest quintile of APOA GRS, whereas HDL-C, LDL-C, APOA, and APOA/APOB were higher (all P < 0.05)." (PMID 33005209, 2020). "They reported that the administration of probiotics of different Lactobacillus and Bifidobacterium species was capable of significantly reducing HbA1c, fasting insulin, and Homeostasis Model Assessment of Insulin Resistance (HOMA-IR) levels and index." (PMID 33023000, 2020). "Increased production of TNF-α in human adipocytes is positively correlated with the degree of obesity, insulin level, and insulin resistance." (PMID 32375231, 2020). "Several disturbances in insulin signal transduction mediated by statin treatment have been described in different organs and tissues leading to a pathologic insulin resistance." (PMID 32630698, 2020). "When there is high insulin resistance, insulin strongly suppresses HSL and activates lipogenesis in hepatocytes." (PMID 33114589, 2020). "The TC, LDL-C levels, insulin, insulin resistance, and uric acid significantly improved in the blueberry group when compared to baseline and placebo control." (PMID 32466434, 2020). "Analysis of multi-organ signalling network models have also raised doubts about the central role of insulin and insulin resistance in T2D (Kulkarni, Sharda & Watve, 2017)." (PMID 33365205, 2020). "Studies indicated that significantly elevated levels of FFAs lead to skeletal muscle insulin resistance, by dysregulating the steps in the insulin signaling cascade." (PMID 32664532, 2020). "In the current study for the first time, we have shown that the circulating exosomes derived from obese women can result in insulin signaling inhibition which in turn leads to hepatic insulin resistance." (PMID 32322309, 2020). "Short-sleepers had lower rates of high total cholesterol (≥5.0 mmol/L), lower Lp(a) levels and lower rates of increased Lp(a) ≥0.5 g/L, and higher insulin and insulin resistance (assessed by the homeostatic model assessment for insulin resistance (HOMA-IR))." (PMID 32630105, 2020). "Type 2 Diabetes (T2DM) is a worldwide epidemic characterized by insulin resistance and abnormal insulin secretion, which can result in severe complications and increased medical care costs." (PMID 32454945, 2020). "Since the adipose tissue insulin resistance is often associated with systemic insulin resistance, we conducted glucose tolerance test (GTT) and insulin tolerance test (ITT)." (PMID 31924774, 2020). "Increased insulin levels, due to insulin resistance (IR) also directly correlated with BC relapse and mortality." (PMID 32500397, 2020). "IAPP can also induce peripheral insulin resistance by antagonising insulin activity, further linking to the overexpression of glycogen synthase kinase-3 (GSK-3)." (PMID 32283762, 2020).
Insulin resistance (continued). "Despite the effects of insulin resistance on glucose uptake and resulting hyperglycaemia, it has been shown that the insulin-induced coronary vasodilation still occurs in obese patients with insulin resistance." (PMID 31953778, 2020). "In the case of T2DM or insulin resistance, the insulin-stimulated glucose transport and skeletal muscle uptake glucose are impaired, which affect glycogen synthesis." (PMID 32922365, 2020). "In other words, the HC group were systemically more resistant to insulin, as indicated quantitatively by their fasting homeostatic model assessment of insulin resistance (HOMA-IR) values of 7.3 compared to 3.1 μIU × mg/[mL]2 in the LC group (P < 0.0008)." (PMID 32699301, 2020). "Insulin resistance is defined as impaired sensitivity to insulin (normal or elevated), which mediates glucose disposal." (PMID 32781523, 2020). "Ingestion of high carbohydrate diets can raise blood glucose, insulin and triglycerides, leading to insulin resistance." (PMID 32867226, 2020). "Due to the continuous insulin resistance and reduction of insulin secretion ability, an enhanced response in the normal beta cells occur to increase insulin and islet amyloid peptide levels." (PMID 33552973, 2020). "The significant (p < 0.001) increased insulin resistance (IR), β-cell function (β%), and insulin sensitivity (S%) were seen in the diabetic group in comparison to the vehicle control group." (PMID 33737876, 2020). "To monitor insulin resistance, we performed an insulin response test on the abdominal fat body tissue by assessing AKT phosphorylation." (PMID 32197072, 2020). "The liver is also another main insulin-sensitive tissue that is also involved in the development of insulin resistance." (PMID 32411098, 2020). "These prospective studies reported on a number of dysglycemia outcomes including blood glucose levels and HbA1c, insulin resistance, 2-h glucose, insulin sensitivity (e.g., HOMA-IR), and incident dysglycemia or type 2 diabetes." (PMID 32563261, 2020). "PWH had significantly higher fasting plasma glucose, higher insulin concentrations, and insulin resistance." (PMID 33007928, 2020). "It has been suggested that chronic exposure to high glycemic index and high glycemic load diets stimulate more production of insulin, resulting in hyper-insulinemia and insulin resistance due to the pancreas exhaustion and failure." (PMID 32670384, 2020). "Elevated levels of free fatty acids resulting from resistance of adipose tissue to insulin can further aggravate insulin resistance in a reciprocally potentiating manner." (PMID 33167495, 2020). "Insulin resistance triggers a rise in insulin demand and leads to β-cell compensation by increasing both β-cell mass and insulin secretion and leads to the development of hyperinsulinemia." (PMID 32150819, 2020). "The combination of increased insulin resistance and insufficient insulin response during pregnancy seems to be the main pathophysiological mechanism responsible for GDM development." (PMID 32785102, 2020). "Insulin resistance occurs when insulin-sensitive tissues fail to respond toinsulin, a phenomenon that is often observed in obesity." (PMID 32999709, 2020). "Hepatic insulin resistance refers to the decreased ability of insulin to inhibit hepatic glucose production (HGP)." (PMID 32132984, 2020). "A maternal HFD induced insulin resistance and deterioration of pancreatic β-cell function in adult offspring at 20 weeks of years, accompanied by decreased insulin content and pancreatic homeobox 1 (PDX-1) mRNA levels in isolated islets." (PMID 32607287, 2020). "Animal studies show that both short-term and chronic HFD consumption results in glucose intolerance and insulin resistance as well as increased fasting glucose, insulin, free fatty acid, triglyceride, and leptin levels compared to regular chow diet." (PMID 33574742, 2020).
Insulin resistance (continued). "It is generally accepted, that saturated FAs like palmitate induce insulin resistance, whereas the monounsaturated ones like oleate increase insulin sensitivity in diabetic patients and healthy individuals." (PMID 32947855, 2020). "Our results demonstrate that tesaglitazar delivered as a standard oral formulation effectively improves indices of insulin resistance and lowers circulating levels of triglycerides, insulin, and glucose." (PMID 31903139, 2020). "The studies we included aimed to analyze the impact of RSV supplementation on different NAFLD related parameters, e.g., liver enzymes, lipid and insulin levels, insulin resistance, and others." (PMID 32823621, 2020). "We searched the databases using the following keywords: Alzheimer's disease, insulin signaling pathway, type 3 diabetes, type 2 diabetes, insulin, and insulin resistance." (PMID 32190448, 2020). "The insulin metabolism contains many players, which also impact the formation of insulin resistance." (PMID 32524217, 2020). "In a clinical test, a decline in fasting blood glucose and insulin secretion of patients treated with CA for 12 weeks, suggested that CA can ameliorate insulin resistance and enhance insulin sensitivity." (PMID 32566690, 2020). "The clinical treatment of T2DM mainly targets insulin resistance and relative insulin secretion; however, glycemic control in diabetic patients is still hard." (PMID 32280711, 2020). "However, it remains to be established whether the observed increase in insulin resistance might contribute to fetal metabolic programming, reflected by a decrease in post-natal insulin sensitivity and increased risk of obesity, glucose intolerance and type 2 diabetes in adults." (PMID 32778645, 2020). "In carnivorous fish, glucose intolerance was usually considered as a consequence of poor peripheral insulin action or possibly “insulin resistance”." (PMID 32754117, 2020). "Insulin resistance in insulin-sensitive tissues will be further discussed in the following sections." (PMID 32183037, 2020). "CD62L−/− mice further displayed lower serum insulin levels and significantly decreased insulin resistance as evidenced by the HOMA-score." (PMID 32365632, 2020). "Insulin resistance is a clinical pathological condition characterized by glucose intolerance and impaired insulin sensitivity." (PMID 32393087, 2020). "It is known that obesity, especially the central obesity, mainly participates in the formation and development of insulin resistance by affecting the sensitivity of insulin." (PMID 32004418, 2020). "TTK was reported to reduce oxidative stress and inflammation and attenuate insulin resistance by potentiating insulin signaling in an insulin-resistant animal model." (PMID 32326255, 2020). "Pregnancy induces peripheral insulin resistance, which is normally compensated by increased β-cell proliferation, expansion of islet volume, and increased insulin synthesis and secretion." (PMID 32872540, 2020). "At present, the mechanism of hypoglycemia mainly includes insulin stimulation and repair of damaged pancreas; effects on glucose metabolism; increases insulin sensitivity, improves insulin resistance, and regulates intestinal flora." (PMID 31936853, 2020). "We further studied the role of short-term hyperlipidemia mediated insulin resistance induced by intravenous administration of intralipid via lipid clamp and insulin administration via HIEC on plasma levels of endocrine FGFs and fetuin-A." (PMID 33101202, 2020). "TNF-α can hinder insulin signaling by inducing the expression of signal transduction inhibitor 3, leading to insulin resistance (IR)." (PMID 33708118, 2020). "Reports indicated that PPAR agonists are insulin sensitizers and improve insulin resistance with T2DM patients." (PMID 33382706, 2020). "Medications that reduce insulin resistance include biguanides and thiazolidinediones, which have insulin-sensitizing and antihyperglycemic effects." (PMID 33287109, 2020).
Insulin resistance (continued). "Our results suggested that LBP reduced glucose levels and insulin resistance, increased testosterone levels and insulin sensitivity, and decreased testicular oxidative stress and pathological damage in obese mice." (PMID 32528287, 2020). "The predictive ability (assessed by AUCs) of TyG index for predicting prediabetes was 0.60 (0.58–0.62), which was superior to the indices of obesity, lipid profiles and other non-insulin-based insulin resistance indices." (PMID 33059672, 2020). "The lack of associations with the other outcomes persisted after adjustment for insulin levels, insulin resistance and height." (PMID 32548700, 2020). "Inhibition of Aurora-A did not affect fasting blood glucose and body weight, but did improve insulin resistance, as indicated by improved oral glucose tolerance, insulin tolerance, and the Homoeostasis Model Assessment-Insulin Resistance index." (PMID 33043822, 2020). "As the main outcome of the present review was insulin resistance or insulin sensitivity at least one parameter was reported." (PMID 33292434, 2020). "Higher insulin levels and insulin resistance in obese as compared to normal weight has also been reported before in a small cohort measured at one time point (mean gestational age week 9)." (PMID 33154737, 2020). "One positive finding was that CRP levels had a positive correlation with fasting blood insulin levels in both diet groups, which is similar to the previous report regarding the chronic systemic inflammation, BMI, insulin resistance and CRP." (PMID 32824387, 2020). "In this case, corticosteroids and metformin permitted withdrawal of insulin and ameliorated insulin resistance symptoms." (PMID 32755965, 2020). "The combination of elevated plasma glucose but with a maintained plasma insulin level in these HFD/STZ rats is consistent with insulin resistance." (PMID 33716721, 2020). "We selected HOMA-IR and HOMA-β as measures of insulin resistance and insulin secretion, respectively, due to the availability of large sets of GWAS data on these traits, comprising over 46,186 non-diabetic participants." (PMID 32294959, 2020). "Ghrelin levels were found to be inversely correlated with parameters of hyperandrogenism, insulin levels, and insulin resistance." (PMID 32442310, 2020). "Oxidised omega-6 fatty acids activate the FOXO transducers of the Insulin signaling pathway potentially linking changes in dietary fatty acid balance and proinflammatory states with insulin resistance." (PMID 31992650, 2020). "By degrading Angiotensin 2, ACE2 protects against the effects of RAAS overactivation, reducing insulin resistance by decreasing cellular oxidative stress, enhancing insulin signaling and insulin-stimulated glucose transport activity." (PMID 32574288, 2020). "Berberine can increase insulin sensitivity in patients, reduce blood sugar, improve insulin resistance, and achieve the therapeutic effect of treating PCOS." (PMID 32785222, 2020). "Adipokines affect insulin resistance both by inducing insulin secretion directly and by regulating PI3K/Akt signaling mediated by insulin indirectly." (PMID 32971772, 2020). "Of note, during the acceleration of adipose content, dysfunctional AT leads to defects in insulin sensitivity and the development of insulin resistance." (PMID 33021706, 2020). "Insulin resistance represents a partial breakdown in communication between these tissues, where insulin target tissues become resistant to insulin signaling, despite initial compensation by the pancreas." (PMID 32140136, 2020). "Some metabolic perturbations, such as B-cell dysfunction, impaired insulin secretion, insulin resistance, and dyslipidemia contribute to the pathogenesis of diabetes." (PMID 32863846, 2020). "The blood glucose, insulin level, β-cell function, insulin resistance, hepatic enzymes, lipid profile, and histology of the liver, and pancreas were evaluated." (PMID 32821355, 2020).